LAPTM4A (lysosomal protein transmembrane 4 alpha)
Description:
May function in the transport of nucleosides and/or nucleoside derivatives between the cytosol and the lumen of an intracellular membrane-bound compartment.
Synonyms: KIAA0108; LAPTM4; MBNT; MTRP; HUMORF13
Tractability: Antibody: UniProt predicts a signal peptide or a membrane-spanning region; the Human Protein Atlas places it where antibodies can reach. PROTAC: ubiquitination databases record sites on it.
Gene: Protein-coding gene on chromosome 2 (20,032,649 to 20,051,693, reverse strand). Ensembl gene ENSG00000068697.
Subcellular location: Endomembrane system
Subcellular location (Human Protein Atlas): Golgi apparatus; Vesicles; Plasma membrane
Gene Ontology:
Molecular function: protein binding
Biological process: regulation of lysosomal membrane permeability
Cellular component: Golgi apparatus; late endosome membrane; lysosomal membrane; endomembrane system; membrane
Genetic constraint (gnomAD): Loss-of-function variants: 12 observed, 16.53 expected, observed/expected ratio (o/e) 0.73, 90% interval 0.46 to 1.18. The upper end of that interval is the gene's LOEUF score, 1.18, which puts it in group 5 of 6, group 1 being the genes least tolerant of losing a copy. Missense variants: 237 observed, 231.23 expected, observed/expected ratio (o/e) 1.02, 90% interval 0.92 to 1.14. Synonymous variants: 84 observed, 83.77 expected, observed/expected ratio (o/e) 1, 90% interval 0.84 to 1.2.
Homologues: Orthologues: chimpanzee LAPTM4A (100% identical), macaque LAPTM4A (99% identical), dog LAPTM4A (98% identical), pig LAPTM4A (98% identical), rat Laptm4a (98% identical), mouse Laptm4a (97% identical), rabbit LAPTM4A (93% identical), guinea pig LAPTM4A (82% identical), zebrafish laptm4a (77% identical), tropical clawed frog laptm4a (76% identical), Drosophila melanogaster CG14767 (31% identical). Paralogues in human: LAPTM4B (44% identical), LAPTM5 (24% identical).
Diseases named in the same sentence as LAPTM4A in open-access papers:
LAPTM4A is named in the same sentence as 15 diseases in open-access papers, as found by Europe PMC text mining. Sharing a sentence is not in itself a finding about the gene and the disease. The quoted sentences say what the papers report.
glioma (2 papers, 2024 to 2026). A benign or malignant brain and spinal cord tumor that arises from glial cells (astrocytes, oligodendrocytes, ependymal cells). "Previous pathway enrichment analyses have established a strong association between LAPTM4A and immune-related pathways in gliomas." (PMID 38613802, 2024). "Through analysis using the cBioPortal website, we determined that the mutation rate of LAPTM4A in gliomas was generally low, with amplification being the most common alteration." (PMID 38613802, 2024). "Based on these findings, we sought to explain the aberrant overexpression of LAPTM4A in gliomas from the perspectives of methylation status and mutations." (PMID 38613802, 2024). "Further, our study suggested that LAPTM4A is a potential prognostic biomarker associated with immune infiltration in glioma." (PMID 38613802, 2024). "However, a detailed examination of copy number variation revealed significant differences in LAPTM4A expression among neutral, gain, and loss groups in glioma." (PMID 38613802, 2024). "Notably, we discovered an association between LAPTM4A expression and neoplasm-related mutant genes in glioma." (PMID 38613802, 2024). "In addition, we discovered that LAPTM4A in glioma patients had a survival and diagnostic value." (PMID 38613802, 2024). "Preclinical data link LAPTM5 to stroke outcomes via stress-kinase and lysosomal pathways, while LAPTM4A and LAPTM4B associate with glioma progression, immune evasion, and therapy resistance." (PMID 41666016, 2026). "Taken together, our findings suggest that LAPTM4A plays an essential role in immune infiltration and immune system function in gliomas." (PMID 38613802, 2024). "Collectively, these findings suggest that LAPTM4A expression is elevated in gliomas and holds promise as a potential biomarker for assessing glioma progression." (PMID 38613802, 2024). "Taken together, our findings provide evidence for the involvement of the FGD5-AS1-hsa-miR-103a-3p-LAPTM4A axis as a regulatory mechanism in glioma progression." (PMID 38613802, 2024). "Taken together, our findings elucidate that the overexpression of LAPTM4A in gliomas can be attributed to both promoter hypomethylation and amplification mutations." (PMID 38613802, 2024). "Our findings showed that mesenchymal subtype gliomas express LAPTM4A more frequently than other subtypes." (PMID 38613802, 2024). "In this study, we endeavored to construct a comprehensive ceRNA regulatory network centered around LAPTM4A in gliomas." (PMID 38613802, 2024). "Our outcomes revealed that the majority of immune-related molecules were co-expressed with LAPTM4A and positively correlated with LAPTM4A in gliomas." (PMID 38613802, 2024). "Through a series of comprehensive and rigorous bioinformatics analyses, complemented by experimental validation, this research establishes LAPTM4A as a novel and potent prognostic factor and therapeutic target for gliomas." (PMID 38613802, 2024). "In conclusion, we found the high expression and better prognostic and diagnostic value of LAPTM4A in glioma and LGG and GBM subtypes and explored that LAPTM4A most probably promoted glioma progression through EMT or immunosuppression pathways." (PMID 38613802, 2024). "We utilized the computational biology method and integrated multi-database to identify the most relevant and clinically relevant gene for glioma, LAPTM4A." (PMID 38613802, 2024). "In conclusion, our findings support the conclusion that overexpression of LAPTM4A is predictive of an unfavorable prognosis in gliomas." (PMID 38613802, 2024). "In conjunction with previous findings, we observed an increase in LAPTM4A expression with increasing grade, while the level of LAPTM4A methylation decreased with glioma grade." (PMID 38613802, 2024). "Given the significance attributed to hsa-miR-103a-3p and hsa-miR-107 in glioma, as elucidated by pertinent literature, we proceeded to investigate the relationship between LAPTM4A expression and these two miRNAs in glioma." (PMID 38613802, 2024).
glioma (continued). "Collectively, our findings illuminate the intricate regulatory mechanism governing LAPTM4A, underscoring the significance of the FGD5-AS1-hsa-miR-103a-3p-LAPTM4A axis in the regulation of glioma progression." (PMID 38613802, 2024). "To explore the expression discrepancies of LAPTM4A among these subtypes, we assessed LAPTM4A expression levels in the Bao, Phillips, and glioma Rembrandt datasets." (PMID 38613802, 2024). "In conclusion, LAPTM4A plays a significant role in multiple immune-related and cancer-relevant pathways in glioma." (PMID 38613802, 2024). "It has been shown that doxorubicin is currently recognized as an effective anticancer agent for glioma treatment, and our research supports the administration of doxorubicin to patients with elevated LAPTM4A expression." (PMID 38613802, 2024). "Given that LAPTM4A is a potential prognostic factor in glioblastoma, we are eager to unravel the involvement of LAPTM4A in the biological processes of gliomas." (PMID 38613802, 2024). "The results of our study brought strong evidence that LAPTM4A was aberrantly over-expressed in human glioma tissues, which was related to poor survival, clinicopathological characteristics, and clinical subtypes." (PMID 38613802, 2024). "Therefore, our study aims to investigate the prognostic value of LAPTM4A in glioma patients and shed light on its biological functions within gliomas." (PMID 38613802, 2024). "In vitro experiments indicated that LAPTM4A may influence metastasis through the EMT pathway in glioma." (PMID 38613802, 2024). "Furthermore, we investigated the correlation between the expression of RP2 and LAPTM4A and the clinicopathological features of glioma patients using the CGGA database." (PMID 38613802, 2024). "In summary, the downregulation of LAPTM4A expression may hold promise for enhancing the efficacy of immunotherapy in glioma patients." (PMID 38613802, 2024). "In particular, in vitro experiments suggest that LAPTM4A may affect glioma metastasis through the EMT pathway." (PMID 38613802, 2024). "In addition, the FGD5-AS1-hsa-miR-103a-3p-LAPTM4A axis was established to reveal the potential regulation mechanisms of glioma." (PMID 38613802, 2024). "With this in mind, we hypothesized the existence of an FGD5-AS1-hsa-miR-103a-3p-LAPTM4A axis in regulating glioma progression." (PMID 38613802, 2024). "Results revealed widespread hypomethylation at the LAPTM4A promoter sites in glioma samples, with differential methylation levels observed across different subtypes, displaying a trend of decreasing methylation levels with increasing glioma grades." (PMID 38613802, 2024). "Ultimately, we found that the FGD5-AS1-hsa-miR-103a-3p-LAPTM4A axis promoted glioma metastasis." (PMID 38613802, 2024). "Finally, we uncovered the FGD5-AS1-hsa-miR-103a-3p-LAPTM4A axis as a facilitator of glioma progression." (PMID 38613802, 2024). "Interestingly, in combination with the CTD database, doxorubicin, which reduces LAPTM4A expression, has better efficacy in glioma patients with high LAPTM4A expression." (PMID 38613802, 2024). "Notably, of these rigorously selected genes, RP2 and LAPTM4A demonstrated not only independent prognostic values for glioma patients but also displayed high Area Under ROC Curve (AUC) values." (PMID 38613802, 2024). "Finally, doxorubicin may be used to reduce the expression of LAPTM4A to improve the treatment of glioma patients." (PMID 38613802, 2024). "However, the role of LAPTM4A in gliomas remains largely unknown, with limited biomedical research conducted on this topic." (PMID 38613802, 2024). "This suggests that LAPTM4A may regulate the progression of gliomas through immune pathways." (PMID 38613802, 2024). "Our study aimed to determine the methylation status of LAPTM4A across different subtypes and WHO grades of glioma." (PMID 38613802, 2024).
glioma (continued). "Furthermore, the knockdown of LAPTM4A may not only be beneficial for immunotherapy but combined with doxorubicin administration may also bring greater therapeutic benefit to patients with glioma." (PMID 38613802, 2024). "Furthermore, the expression levels of LAPTM4A in glioma tissue demonstrated a negative correlation with miR-103a-3p." (PMID 38613802, 2024).
prostate carcinoma (2 papers, 2015 to 2026). A carcinoma that arises from epithelial cells of the prostate gland. "Other proteins enriched in prostate cancer proteins such as LAPTM4A, RAB7A, AFAP, and TSPAN6 are putative targets for CRL1 as detected by screening with a NEDD8 activating enzyme inhibitor." (PMID 26196085, 2015).
colorectal carcinoma (1 paper, 2018). A malignant epithelial neoplasm that arises from the colon or rectum and invades through the muscularis mucosa into the submucosa. "Interestingly, a recent genome-wide CRISPR-Cas9 screen, carried out by incubating EHEC with human colorectal carcinoma cell line HT-29, also identified LAPTM4A and TM9SF2 as key factors for EHEC toxicity to cells." (PMID 30481169, 2018).
gallbladder cancer (1 paper, 2017). "In this regard, the amplification of laptm4a and laptm4b genes has been reported in numerous chemoresistant tumors, including breast and gallbladder cancer." (PMID 29292724, 2017).
glioblastoma (1 paper, 2024). The most malignant astrocytic tumor (WHO grade IV). "The results demonstrated that the knockdown of LAPTM4A inhibited the invasion and migration of glioblastoma cells." (PMID 38613802, 2024). "Collectively, our findings suggest that suppression of LAPTM4A expression may hinder glioblastoma invasion and migration through the EMT pathway." (PMID 38613802, 2024).
HIV-1 infection (1 paper, 2021). The type species of lentivirus and the etiologic agent of acquired immunodeficiency syndrome (AIDS). "We mechanistically probed how LAPTM5 combats HIV-1 infection by investigating LAPTM5 and the other LAPTM family members LAPTM4A and 4B." (PMID 34140527, 2021).
cancer (5 papers, 2011 to 2024). A tumor composed of atypical neoplastic, often pleomorphic cells that invade other tissues. "Given the strongly positive association between LAPTM4A and monocytes/macrophages, as well as cancer-associated fibroblasts, we further examined the relationship between LAPTM4A and their biomarkers at the mRNA level." (PMID 38613802, 2024). "In our study, the TIMER2 website showed a significant positive correlation between LAPTM4A and monocyte/macrophage and cancer-associated fibroblast infiltration." (PMID 38613802, 2024). "Moreover, utilizing the TCGA database, we demonstrated the association between immune and cancer-associated pathways and LAPTM4A expression." (PMID 38613802, 2024). "In addition to the enrichment of guides targeting TM9SF2, LAPTM4A, and genes related to sphingolipid biosynthesis, our analysis detected enrichment for guides targeting several genes associated with cancer and cell proliferation (MLLT3, TFAP4, ZNF217, and DUSP6) (35, –, 38)." (PMID 29921669, 2018). "In order to identify the key cell types expressing LAPTM4A within the cancer microenvironment, we conducted a comprehensive single-cell analysis of LAPTM4A across 80 cancer sample datasets." (PMID 38613802, 2024). "The Lysosome associated protein transmembrane (LAPTM) family is comprised of three members: LAPTM5, LAPTM4a and LAPTM4b, with the latter previously shown to be overexpressed in numerous cancers." (PMID 22096579, 2011). "Notably, our findings highlighted a predominant expression of LAPTM4A in immune cells, particularly monocytes and macrophages, across various cancer types." (PMID 38613802, 2024). "Not only that, our results also reveal a positive correlation between LAPTM4A and multiple immune checkpoint (ICP) gene expressions, including the well-known CD274, PDCD1, and CD80, which tend to suppress effector T cells to promote cancer development." (PMID 38613802, 2024).
tumor (3 papers, 2019 to 2025). "LAPTM4A is highly expressed in a variety of tumor tissues and is considered a significant risk factor for patients with PAAD." (PMID 40141028, 2025). "As EMT programming has been implicated in the metastasis of malignant tumor cells originating from epithelial cells, we further explored the relationship between LAPTM4A expression and tumor metastasis using the Transwell assay." (PMID 38613802, 2024). "Moreover, our analysis revealed that LAPTM4A is primarily associated with immunity and is expected to become an encouraging therapeutic target for tumor immunotherapy." (PMID 38613802, 2024). "Additionally, we found that LAPTM4A was associated with the tumor microenvironment (TME) and immunotherapy." (PMID 38613802, 2024). "LAPTM4A’s relationship with immune cell infiltration and tumor drug sensitivity has implications for patient prognosis." (PMID 40141028, 2025). "We first elaborated that LAPTM4A expression was closely correlated with the degree of tumor immune infiltration by stromal score, immune score, and estimation score." (PMID 38613802, 2024). "Human LAPTM4A has 46% amino acid homology with human LAPTM4B, another LAPTM family member involved in tumor progression and lysosomal ceramide transport." (PMID 30660999, 2019).
infection (2 papers, 2018 to 2019). The state of being infected such as from the introduction of a foreign agent such as serum, vaccine, antigenic substance or organism. "To gain greater insight into the mechanism by which TM9SF2 and LAPTM4A enable infection by EHEC, we determined their subcellular localization in HeLa cells via confocal microscopy." (PMID 29921669, 2018). "Intriguingly, the TM9SF2 and LAPTM4A mutants were also significantly more abundant than wt cells by 5 days post-ΔescN mutant infection, suggesting that these factors not only contribute to resistance to T3SS-mediated cytotoxicity, but also could be host factors facilitating intoxication." (PMID 29921669, 2018).
neurological disease (1 paper, 2026). "Lysosomal-associated protein transmembrane (LAPTM) family members-LAPTM4A, LAPTM4B, and LAPTM5-regulate lysosomal integrity, autophagy-lysosome flux, lipid homeostasis, and immune signaling, pathways increasingly implicated in neurological disease." (PMID 41666016, 2026).
LAPTM4A also shares sentences with these, for which no sentence is quoted: acute kidney injury (1 paper); breast carcinoma (1); mastitis (1); scrapie (1); Stroke (1).